Y_RNA (Y RNA )
Gene: Miscellaneous RNA gene on chromosome 3 (101,628,310 to 101,628,406, reverse strand). Ensembl gene ENSG00000212319.
Homologues: Orthologues: chimpanzee Y_RNA (100% identical), guinea pig Y_RNA (80% identical). Paralogues in human: RNY4 (84% identical), RNY4P19 (82% identical), RNY4P6 (82% identical), RNY4P10 (81% identical), RNY4P23 (81% identical), Y_RNA (81% identical), RNY4P13 (80% identical), RNY4P25 (80% identical), Y_RNA (80% identical), RNY4P37 (79% identical), Y_RNA (79% identical), RNY4P27 (78% identical), and 89 more.